CHMP6 (charged multivesicular body protein 6)
Description:
Probable core component of the endosomal sorting required for transport complex III (ESCRT-III) which is involved in multivesicular bodies (MVBs) formation and sorting of endosomal cargo proteins into MVBs. MVBs contain intraluminal vesicles (ILVs) that are generated by invagination and scission from the limiting membrane of the endosome and mostly are delivered to lysosomes enabling degradation of membrane proteins, such as stimulated growth factor receptors, lysosomal enzymes and lipids. The MVB pathway appears to require the sequential function of ESCRT-O, -I,-II and -III complexes. ESCRT-III proteins mostly dissociate from the invaginating membrane before the ILV is released. The ESCRT machinery also functions in topologically equivalent membrane fission events, such as the terminal stages of cytokinesis and the budding of enveloped viruses (HIV-1 and other lentiviruses). ESCRT-III proteins are believed to mediate the necessary vesicle extrusion and/or membrane fission activities, possibly in conjunction with the AAA ATPase VPS4. In the ESCRT-III complex, it probably serves as an acceptor for the ESCRT-II complex on endosomal membranes.
Synonyms: Vps20; FLJ11749
Tractability: Antibody: its Gene Ontology location is reachable by antibodies, with high confidence; UniProt places it where antibodies can reach, with medium confidence. PROTAC: UniProt records ubiquitination sites on it; ubiquitination databases record sites on it; its protein half-life has been measured.
Gene: Protein-coding gene on chromosome 17 (80,991,598 to 81,009,517, forward strand). Ensembl gene ENSG00000176108.
Subcellular location: Endomembrane system; Endosome membrane; Late endosome membrane; Membrane
Pathways (Reactome):
Disease: Budding and maturation of HIV virion; HCMV Late Events; Translation of Replicase and Assembly of the Replication Transcription Complex
Autophagy: Late endosomal microautophagy; Macroautophagy
Cell Cycle: Sealing of the nuclear envelope (NE) by ESCRT-III
Programmed Cell Death: Pyroptosis
Vesicle-mediated transport: Endosomal Sorting Complex Required For Transport (ESCRT)
Gene Ontology:
Molecular function: protein binding; protein-containing complex binding
Biological process: autophagosome maturation; autophagy; late endosome to lysosome transport; midbody abscission; mitotic metaphase chromosome alignment; multivesicular body sorting pathway; negative regulation of epidermal growth factor-activated receptor activity; nuclear membrane reassembly; nucleus organization; plasma membrane repair; regulation of exosomal secretion; regulation of mitotic spindle assembly; regulation of protein catabolic process; ubiquitin-dependent protein catabolic process via the multivesicular body sorting pathway; viral budding from plasma membrane; viral budding via host ESCRT complex; ESCRT III complex assembly; late endosome to vacuole transport via multivesicular body sorting pathway; macroautophagy; membrane fission; multivesicular body assembly; multivesicular body-lysosome fusion; vesicle fusion with vacuole; vacuolar transport
Cellular component: amphisome membrane; autophagosome membrane; endosome membrane; ESCRT III complex; extracellular exosome; kinetochore; kinetochore microtubule; lysosomal membrane; membrane; midbody; multivesicular body membrane; nuclear pore; plasma membrane; cytosol; nuclear envelope; endomembrane system; late endosome membrane
Genetic constraint (gnomAD): Loss-of-function variants: 10 observed, 28.3 expected, observed/expected ratio (o/e) 0.35, 90% interval 0.22 to 0.6. The upper end of that interval is the gene's LOEUF score, 0.6, which puts it in group 2 of 6, group 1 being the genes least tolerant of losing a copy. Missense variants: 269 observed, 246.81 expected, observed/expected ratio (o/e) 1.09, 90% interval 0.99 to 1.21. Synonymous variants: 123 observed, 99.13 expected, observed/expected ratio (o/e) 1.24, 90% interval 1.07 to 1.44.
Homologues: Orthologues: guinea pig CHMP6 (94% identical), mouse Chmp6 (93% identical), macaque CHMP6 (92% identical), pig CHMP6 (92% identical), rat Chmp6 (83% identical), tropical clawed frog chmp6 (69% identical), zebrafish chmp6b (68% identical), zebrafish chmp6a (61% identical), Drosophila melanogaster Vps20 (51% identical), Caenorhabditis elegans vps-20 (45% identical).
Diseases named in the same sentence as CHMP6 in open-access papers:
CHMP6 is named in the same sentence as 18 diseases in open-access papers, as found by Europe PMC text mining. Sharing a sentence is not in itself a finding about the gene and the disease. The quoted sentences say what the papers report.
breast carcinoma (2 papers, 2022 to 2023). "Studies on the prognosis of breast cancer tumors have shown that CHMP6, a pyroptosis-death-associated gene, is significantly downregulated in breast cancer." (PMID 37542283, 2023).
colorectal cancer (2 papers, 2022). A primary or metastatic malignant neoplasm that affects the colon or rectum. "However, the role of CHMP2B, BID and CHMP6 in colorectal cancer have not been reported yet, which may provide new biomarkers for future research on the relationship between necrosis and colorectal cancer." (PMID 35783272, 2022).
COVID-19 (2 papers, 2022 to 2023). A disease caused by infection with severe acute respiratory syndrome coronavirus 2. "Here, four hub genes including MVB12A, CHMP6, STAM, and VPS37B were considered to be involved in the core regulation of autophagy in severe COVID-19 cases." (PMID 35923698, 2022). "Therefore, MVB12A, CHMP6, STAM, and VPS37B were regarded as hub genes regulating autophagy in severe COVID-19." (PMID 35923698, 2022).
bladder cancer (1 paper, 2025). "We constructed CHMP6 knockdown human bladder cancer cell lines and utilized WB and Q-pcr techniques for validation at the protein level and RNA level, and in the cell lines with CHMP6 knockdown, we found that ACSL5 protein levels were elevated." (PMID 40630215, 2025).
Lymphadenopathy (1 paper, 2025). Enlargement (swelling) of a lymph node. "A nomogram based on the most predictive clinical variables (age, Tis (in situ), gender, history of NMIBC, and lymphadenopathy) and genes selected following the Akaike information criterion (AIC) (CBTB16, CHMP6, DDX54, CASP8, LOR, and PLEC) was then created." (PMID 40149716, 2025).
lymphoma (1 paper, 2021). A malignant (clonal) proliferation of B- lymphocytes or T- lymphocytes which involves the lymph nodes, bone marrow and/or extranodal sites. "Additionally, there was an enrichment of CHMP6 variants in lymphoma vs. CLL patients (Fisher’s p-value 0.02, q-value 0.04)." (PMID 33809641, 2021).
triple-negative breast carcinoma (1 paper, 2022). An invasive breast carcinoma which is negative for expression of estrogen receptor (ER), progesterone receptor (PR), and human epidermal growth factor receptor 2 (HER2). "Previous studies reported that CHMP6 was significantly down-regulated across several kinds of cancers including BRCA, especially in triple-negative breast cancer." (PMID 35957895, 2022).
tumor (16 papers, 2014 to 2025). "In the 27 PRGs, apart from CASP4, CHMP6, CHMP7, GSDMD, and TP63, the other 22 PRGs were expressed differentially at a significant level between primary tumor and paracancerous samples." (PMID 35938142, 2022). "Seven pyroptosis-related genes (ELANE, IL18, CHMP2B, CHMP4C, CASP9, CHMP6, and CHMP2A) were downregulated in tumor tissues, while 31 pyroptosis-related genes were upregulated in tumor tissues." (PMID 35432539, 2022). "CHMP2B, CHMP6, and RIPK3 were downregulated, while CXCL1, GPX4, and TRAF2 were upregulated in tumor samples." (PMID 36046241, 2022). "It demonstrated that the expression of G6PD, EGFR, CHMP6 and PROM2 were elevated in the tumor tissues." (PMID 34885178, 2021). "In summary, three genes in the PRG model (CASP1, CHMP6, and GZMA) is shown to be a protective factor, while the other three genes (CASP4, DHX9, and DFNA5) were defined as tumor-promoting factors." (PMID 34820372, 2021). "Interestingly, PRGs with CNV gain, including GSDMD, GSDMC, CHMP4C and CHMP6, were significantly higher in HCC samples than in adjacent non-tumor samples (p < 0.001), suggesting that CNVs may regulate PRGs expression." (PMID 36650832, 2023).
cancer (9 papers, 2021 to 2025). A tumor composed of atypical neoplastic, often pleomorphic cells that invade other tissues. "This is in agreement with a recent study showing that knock down of CHMP5 or CHMP6 sensitizes cancer cells to ferroptosis." (PMID 33335287, 2021). "The HsVps35, TSG101, and CHMP6 (orthologous of EhVps35, EhVps23, and EhVps32) proteins have been widely studied in multiple cellular processes, such as cell migration, secretion, and cell proliferation in cancer." (PMID 39397861, 2024). "Our screen identified ATG9A along with several ESCRT genes (UBAP1, CHMP6, and VPS25) as critical determinants of the cancer cell response to macrophages." (PMID 40595560, 2025). "CHMP5 or CHMP6 confers resistance to ferroptotic PANC1 and HepG2 human cancer cell death." (PMID 36330465, 2022).
infection (4 papers, 2016 to 2025). The state of being infected such as from the introduction of a foreign agent such as serum, vaccine, antigenic substance or organism. "TSG101, VPS28, MVB12A, and CHMP6 were knocked down individually in 293T cells, followed by infection of the cells with replication-competent HCoV-OC43." (PMID 40407327, 2025). "The HHV6 pU44 vMIM2 binds less tightly (KD = 30.9 μM), but high abundance of pUL71 and homologues at later stages of infection and their potential ability to polymerise would allow them to compete effectively with endogenous CHMP6 for VPS4A binding." (PMID 38900818, 2024). "Our analysis demonstrates that Tsg101 interacts with both upstream complex Hrs and with downstream complex proteins, EAP45 (ESCRT-II), CHMP6 (ESCRT-III) and CHMP5 (ESCRT-III), and CHMP5 and CHMP6 proteins associate with KSHV (glycoprotein gB) particles early during infection." (PMID 27764233, 2016). "There is a mild defect in virus spread in the presence of dominant negative CHMP4B and CHMP6, quantitated via immunocytochemistry of cells expressing immediate early proteins following low MOI infection, but the effect of dominant negative VPS4 on spread was not analysed." (PMID 38900818, 2024).
CHMP6 also shares sentences with these, for which no sentence is quoted: glioma (2 papers); pancreatic cancer (2); cervical carcinoma (1); fronto-temporal dementia (1); liver cancer (1); periodontitis (1); prostate carcinoma (1); Sepsis (1).